TRPV1 (transient receptor potential cation channel subfamily V member 1)
Diseases named in the same sentence as TRPV1 in open-access papers (continued):
Sharing a sentence is not in itself a finding about the gene and the disease.
tumor (continued). "Also, in vitro attenuation of the 5-hydroxytryptamine (HT)2B receptor activity and transient receptor potential vanilloid-1 (TRPV1) inhibited tumor growth and promoted apoptosis." (PMID 35155248, 2022). "Moreover, AEA is considered a full agonist (endovanilloid) at TRPV1 in different tumour cell lines, while 2-AG is weakly active on TRPV1." (PMID 34943903, 2021). "The acid-sensing ion channels ASIC1 and ASIC2, as well as the transient receptor potential vanilloid channels TRPV1 and TRPV4, are proton-gated cation channels that can be activated by low extracellular pH (pHe), which is a hallmark of the tumor microenvironment in solid tumors." (PMID 34199609, 2021). "On this basis, we can hypothesize that TRPV1 loss in differentiated GSCs, which is different from high TRPV1 expression in D-NSC, represents an escape mechanism of tumor cells from death mediated by TRPV1 agonists." (PMID 34440820, 2021). "Importantly, we demonstrate for the first time that down-regulation of TRPV1 expression in GC tissues was correlated with large tumor size, high histological grade, lymphatic metastasis, advanced clinical stage and poor prognosis." (PMID 33008449, 2020). "Therefore, TRPV1 expression was decreased in human primary GC, consistently with the prediction from Oncomine tumor database." (PMID 33008449, 2020). "The tumor-induced local environment acidification can activate TRPV1 at normal body temperatures." (PMID 32960817, 2020). "Moreover, activation of TRPV1 also increases the anti-tumor efficiency of clinical drugs like doxorubicin probably via aggravating the ROS induced apoptosis." (PMID 32211326, 2020). "Importantly, TRPV1 is expressed in neurons and senses signals of pain, whereas tumor-induced bone pain is a severe clinical condition that needs to be addressed." (PMID 32211326, 2020). "TRPV1 is suggested as a novel tumor suppressor and prognosis marker for ccRCC and might be of great value for further researching." (PMID 32913462, 2020). "Furthermore, a few studies previously shown that TRPV1 was likely involved in tumor progression, and its activation reduced cell proliferation, migration and invasion in breast cancer, urothelial cancer and papillary thyroid carcinoma." (PMID 33008449, 2020). "Therefore, mechanistically, TRPV1 blocked cell cycle at G1 phase to inhibit GC cell proliferation in vitro and tumor growth in vivo." (PMID 33008449, 2020). "We have verified that TRPV1 expression is downregulated in human primary GC tissues compared to their adjacent tissues, which is consistent with the prediction from the Oncomine tumor database." (PMID 33008449, 2020). "Since curcumin has a vanilloid structure with a vanilloid-like activity via a selective binding to TRPV1, TRPV1 activation by curcumin could be a possible mechanism to induce cell death and prevent tumor growth." (PMID 30087301, 2018). "In bladder transitional cell carcinoma TRPV1 expression declines with the increase of tumor grade." (PMID 30087301, 2018). "Further careful studies are required to determine whether the effects of TRPV1 signaling differ according to tumor site." (PMID 28081185, 2017). "We assumed that endogenous TRPV1 activators together with MRS might be sufficient to impair MCF7 tumor formation." (PMID 28640864, 2017). "We hypothesized that the compound MRS1477 might be able to increase the oxidative stress levels in tumor cells expressing TRPV1 channels that are also producing endogenous TRPV1 agonists." (PMID 28640864, 2017). "Administration of capsazepine, an antagonist for TRPV1, has been found to prevent cutaneous vasodilation, suggesting that capsazepine may be a promising candidate for prevention of tumor growth, although its ability to prevent metastasis remains unclear." (PMID 29108231, 2017). "Since in an otherwise healthy body TRPV1 agonists are only produced in the tumor microenvironment, PAMs of TRPV1 might have tumor-selective cytotoxic effects." (PMID 28640864, 2017).
tumor (continued). "However, exogenous TRPV1 agonists, although reducing tumor cell viability at high concentrations in vitro, fail to induce the overstimulation-based cytotoxicity observed in pain-sensing neurons, even at lower concentrations." (PMID 28640864, 2017). "In addition, to investigate the effect of NGF and TRPV1 on the tumor model, the mixture of AsPc-1 cells and PSCs was co-injected into the pancreases of mice." (PMID 26934446, 2016). "Recently, TRPV-1 activation was reported to induce cell death or suppress tumour growth." (PMID 26888607, 2016). "Results from this study demonstrated that TRPV-1 activation via the combination of 42 °C culture and chemical compounds eliminated iPS cells in cardiac tissue, which may lead to reduced tumour formation following transplantation of iPS cell-derived cells." (PMID 26888607, 2016). "Though exceeding the scope of the present study, the contribution of moonlighting TRPV1 in AEA-stimulated tumor-angiogenesis by endothelial cells awaits further investigation in order to evaluate the therapeutic potential of TRPV1 inhibition against tumor-angiogenesis." (PMID 25395667, 2014). "Our present data may imply a novel approach to circumvent AEA-triggered tumor-angiogenesis of endothelial cells by specifically targeting the putative AEA transport-regulator TRPV1." (PMID 25395667, 2014). "Our present data suggest that the angiogenic effect of tumor-derived AEA on endothelial cells essentially involves TRPV1-mediated uptake of AEA, subsequently followed by activation of intracellular AEA receptors yielding the pro-angiogenic effect of this endocannabinoid." (PMID 25395667, 2014). "It has been reported that microenvironment of tumor tissues has pH values of 4∼5, and that pain behaviors could be induced at a pH as low as 5.0 through activation of ASICs and/or TRPV1." (PMID 20422007, 2010). "Similarly, formaldehyde at 3 mM (concentration detected in human tumor tissues) induced an inward current in TRPV1-CHO cells in a concentration-dependent manner and 10 μM capsazepine blocked the formaldehyde-induced current." (PMID 20422007, 2010). "Low concentrations (1∼5 mM) of formaldehyde induced pain responses in rat via TRPV1 and this pain response could be significantly enhanced by pH 6.0 (mimicking the acidic tumor microenvironment)." (PMID 20422007, 2010). "This implies that formaldehyde secreted by tumor tissues possibly up-regulates TRPV1 expression." (PMID 20422007, 2010). "Therefore, the utilization of TRPV1 agonists could be a complementary approach to current therapeutic agents to promote apoptosis in drug-resistant tumour cells." (PMID 40078961, 2025). "Consequently, the hypothesis that ‘further development and application of TRPV1 agonists can be anti-tumour in terms of inhibiting proliferation’ can be formulated." (PMID 40078961, 2025). "Therefore, future therapeutic strategies should aim to restrict TRPV1 inhibition to the tumor microenvironment—for example, by using nanoparticle-mediated delivery, ligand-conjugated inhibitors, or localized ablation—to maximize efficacy while minimizing systemic adverse effects." (PMID 41009819, 2025). "Given our previous findings that the Src—H3 acetylation axis plays a critical role in tumor cell mechanosignaling—serving as a key transduction pathway in response to 1 Hz mechanical stimulation of OS cells —we hypothesized that TRPV1 activation might be a component of this signaling cascade." (PMID 41009392, 2025). "For example, in cases where TRPV1 activation drives apoptotic pathways, enhancing its activity could be beneficial, while inhibition might be more effective in situations where TRPV1 supports tumor survival and immune evasion." (PMID 39407657, 2024). "Furthermore, in tumor tissue, TRPV1 regulates the infiltration and migration of T cells." (PMID 38734935, 2024). "Such TRPV1 activation could occur in response to low pH or hypoxia, which are both prevalent within the tumor microenvironment." (PMID 39302290, 2024).
tumor (continued). "Furthermore, GDNF secreted by tumor cells might upregulate TRPV1 expression, leading to more pain sensitivity." (PMID 39723256, 2024). "Thus, the role of TRPV1 in different tumors may depend on tumor type and requires further mechanistic studies." (PMID 38734935, 2024). "Indeed, recent studies suggested that TRPV1 is potentially an actionable target that could simultaneously overcome the refractory phenotypes of tumor cells and CIPN30,44,45." (PMID 37165076, 2023). "On the one hand, capsaicin may induce apoptosis in this tumor by activating TRPV1." (PMID 37371563, 2023). "We then questioned whether TRPV1 potentiates the refractory phenotypes of NANOG+ tumor cells." (PMID 37165076, 2023). "Furthermore, EGFR knockdown reduced the resistance of TRPV1-transfected tumor cells to cisplatin." (PMID 37165076, 2023). "However, our study suggests that TRPV1 is likely to act as a tumor suppressor." (PMID 36304985, 2022). "Furthermore, by comparing a regular HGSOC model with a TRPV1+ sensory nerve-deprived transgenic model, they suggested that tumor-infiltrating TRPV1 sensory nerves contribute to tumor growth, particularly carboplatin resistance, which thus results in worse survival." (PMID 35455973, 2022). "The tumor suppressive effect of TRPV1 may be achieved through multiple pathways." (PMID 36304985, 2022). "By a similar mechanism, it may also kill tumor cells which express TRPV1." (PMID 34336669, 2021). "Notably, tumor metastasis in the skeleton has been reported to induce significant bone remodeling and tissue damage that leads to the release of BK and indirect sensitization of TRPV1 and TRPA1 channels or direct activation of TRPA1 channels." (PMID 35053150, 2021). "Moreover, the loss of TRPM3, TRPV1, TRPV2, and TRPML1 expression has been proposed as a negative prognostic marker for GBM patients, because of their significant and progressive down-regulation as the tumor grade increases." (PMID 33928077, 2021). "Interestingly, NPCs accumulate at HGA especially in the context of the juvenile brain, exhibiting a high proliferative activity in the stem cell niche, and can release tumor-suppressive factors, such as endovanilloids able to activate TRPV1 expressed by HGA cells." (PMID 33928077, 2021). "Togetether, these data suggest that TRPV1 might be a tumor suppressor in human GC." (PMID 33008449, 2020). "Therefore, TRPV1 could not only inhibit GC cell proliferation in vitro but also suppress tumor growth in vivo, confirming our early notion that TRPV1 acts as a tumor suppressor in GC." (PMID 33008449, 2020). "Therefore, TRPV1 might offer new therapeutic option in clinical applications against neoplastic diseases and pain treatment." (PMID 31681615, 2019). "Therefore, selective targeting of TRPM8 control of TRPV1 responsiveness to transactivation by VEGF may ultimately provide an alternative approach to reduce tumor growth in a clinical setting." (PMID 30483120, 2018). "Similarly, although the tumor environment was shown to contain endogenous TRPV1 agonists promoting the development of tumors, exogenous agonists such as CAPS might have an opposite, i.e. anti-tumorigenic effect." (PMID 28640864, 2017). "Rather than simply causing the sprouting of existent nerves around the tumour, these mediators may also cause nerves to grow into the tumour, moving up NGF and VEGF gradients as well becoming hyperactive as demonstrated here through enhancement of sensory neuronal TRPV1 activity." (PMID 29100335, 2017). "In addition, we investigated the effect of NGF and TRPV1 on the tumor model." (PMID 26934446, 2016). "This in turn raises an interesting question of whether formaldehyde at pathologically low concentrations (1∼3 mM, based on the concentrations of formaldehyde detected in human tumor tissues) can induce pain responses, and whether TRPV1 or TRPA1 is involved in the pain responses." (PMID 20422007, 2010).
tumor (continued). "Evidence suggests that TRPV1, TRPV2, and TRPV4 are overexpressed in several tumor types, contributing to processes such as tumor survival, proliferation, metastasis (migration and invasion), and angiogenesis." (PMID 40006844, 2025). "While the anti‐tumor potential of cannabinoids in GBM has traditionally been attributed to the modulation of ECS receptors, the roles of GPR55 and TRPV1 have also been the focus of recent investigation." (PMID 40781861, 2025). "For instance, both TRPV1 and TRPM8 can exert either tumor-promoting or tumor-inhibiting effects, depending on the stage of the tumor, the composition of the tumor microenvironment, and the specific intracellular signaling milieu." (PMID 40869148, 2025). "C57BL/6 (black, n=15) and TRPV1-Cre::Floxed-DTA (blue, n=14) mice were orthotopically implanted with MOC2-7 tumor and behavior assessed weekly and statistically analyzed by repeated measures ANOVA." (PMID 39302290, 2024). "Thus, our results suggest that TRPV1, which is functionally active as a Ca2+-permeable cation channel, could confer cisplatin resistance by regulating autophagosome formation in cisplatin-resistant tumor cells." (PMID 37165076, 2023). "GDF11 is a tumor suppressor, Class II genes are mainly tumor suppressor, including GDF11, TRPV1 and HIC1." (PMID 36741321, 2023). "Specifically, TRPV1 agonists markedly increase IFN-γ response in control mice, while the opposite effect occurs in tumor-bearing mice." (PMID 37371563, 2023). "We also demonstrate that both TRPV1 and TRPA1 channels are sensitized to tumor-secreted factors in vitro." (PMID 37111275, 2023). "Owing to the ability of TRPV1 blockade to selectively suppress stressful HSP70, IS-Micelles under light exposure distinctly delayed the tumor growth of large HCT-116 tumor model, as evidenced by the smallest tumor volume and prolonged survival period." (PMID 37120615, 2023). "Thus, TRPV1 deficiency reduced pain-like behavior without interfering with tumor growth." (PMID 36138983, 2022). "Trpv1 was expressed in more than 75% of neurons from sham mice (28/36 male, 31/36 female) and MOC2-tumor bearing mice (26/36 male, 23/36 female)." (PMID 36172037, 2022). "Trpv1 was expressed in about 70% of neurons from sham mice (24/36 male, 27/36 female) and >80% of neurons from MOC1-tumor bearing mice (29/36 male, 34/36 female)." (PMID 36172037, 2022). "In UC, it has been demonstrated that the expression and activity of both TRPV1 and TRPV2 affect tumor stage progression and cell differentiation." (PMID 33477303, 2021). "Concerning TRPV1 and TRPV2, the preventing role in gliomagenesis and tumor progression has been more clearly established and characterized (see next paragraph)." (PMID 33928077, 2021). "The interesting role of TRPV1 channels in GC suppression needs further investigation, but it is not surprising since different Ca2+-permeable channels mediate cellular Ca2+ signals with various temporal and spatial precision, which may play different roles of anti-tumor or pro-tumor." (PMID 33008449, 2020). "Given TRPV1 overexpression and near-infrared (NIR) irradiation at tumor sites, a CuS@CaCO3-PEG nanoplatform can initiate the [Ca2+]i cascade in both cancerous and non-cancerous tissues." (PMID 32545311, 2020). "In this model, the overexpression of TRPV1 in BGC823 cells markedly suppressed growth ability of GC cells after their implantation, leading to significant decreases in both tumor weights by about 52% and tumor volume by about 60% compared to their NC groups." (PMID 33008449, 2020). "The other factor was TRPV1 downregulation aberrantly correlated with PTEN (r = -0.206, P = 1.63e-06), a classic tumor suppressor, and VEGFA (r = -0.493, P = 0e+00), which is widely viewed as a promoting gene of ccRCC." (PMID 32913462, 2020).
tumor (continued). "These channels such as TRPV1, TRPV2, as well as other numerous members of TRP channel family play a critical role in tumorigenesis, tumor vascularization, and the ability of tumor cells to proliferate and migrate." (PMID 31680972, 2019). "To further characterize the nature of mEERL tumor innervation, we performed triple immunofluorescent labeling for β-III tubulin, TRPV1 and Tau (another neuronal marker) on formalin fixed paraffin embedded tumors." (PMID 30327461, 2018). "Fourteen days post-implantation, animals were sacrificed and tumors harvested; n = 5 tumors/group were utilized for whole tumor lysate and western blot analysis for β-III tubulin, Tau and TRPV1." (PMID 30327461, 2018). "Even some approved drugs or novel drugs in clinical trials are available, which modulate some potentially tumor-relevant TRP channels, e.g., GRC 17536 (TRPA1), XEN-D0501 (TRPV1), SB705498 (TRPV1)." (PMID 30248976, 2018). "In order to evaluate the effects of zoledronic acid and paclitaxel on spinal nerve activity, the mRNA levels of c-fos and TRPV1 in the ipsilateral spinal cord, and ASIC3 in the ipsilateral DRG were assessed on days 14 and 21 post-tumor cell inoculation." (PMID 26081451, 2015). "Future work should explore whether pharmacological TRPV1 antagonists, antioxidant compounds, or HIF/ERRα modulators can synergistically mitigate hypoxia-driven Ca2+ dysregulation in ERα-positive tumor models." (PMID 41303593, 2025). "However, TRPV1 regulates the expression and function of VEGF and its receptors and is involved in tumor angiogenesis process, which is still uncertain and needs further study." (PMID 40007993, 2025). "Recent findings also reveal that nociceptive TRPV1-positive nerves infiltrating an adenosine-rich oral SCC microenvironment release α-CGRP upon stimulation of adenosine A2A receptor on trigeminal ganglia, thereby contributing to tumor progression." (PMID 39906323, 2024). "We noted that following SCH58261 treatment, the CGRP signal did not alter in TRPV1+ nerves surrounding tumor xenograft, yet significantly enhanced in intra-tumoral nociceptors." (PMID 38886342, 2024). "The 4T1 BC cells developed the acidic tumor microenvironment in bone and progressively induced BP (BC-induced BP, BCIBP) with increased expression and activation of the acid-sensing nociceptor, transient receptor potential vanilloid-1 (TRPV1) on SNs." (PMID 37461623, 2023). "As a result, the IS-Micelles/aPD-L1 combination yielded TRPV1 blockade-synergized thermo-immunotherapy to efficiently suppress the tumor progression of highly intractable subcutaneous and orthotopic PDAC tumor models through reinvigorated immune responses and relieved immunosuppression." (PMID 37120615, 2023). "Lastly, TRPV1 agonists markedly increase IL-6 secretion in tumor-bearing mice, but not in control mice." (PMID 37371563, 2023). "Ignorable red fluorescence was observed for TRPV1 knockdown in the absence of hyperthermia, indicating a non-toxic property of TRPV1 channel itself on tumor cell apoptosis." (PMID 37120615, 2023). "Notably, TRPV1 inhibition by AMG9810 robustly dampened EGFR or AKT phosphorylation and downregulated MCL1 expression in the tumor cells." (PMID 37165076, 2023). "Below, the possible causes of these discrepancies are discussed, focusing on non-neuronal TRPV1 activation, as well as the neuronal components of the tumor microenvironment." (PMID 37371563, 2023). "Distinctly, the TRPV1 blockade plays a crucial role in yielding an effective inhibition against distal metastatic nodules arising from their involvement in regulation of EMT pathways, although IS-Micelles only exert the local hyperthermia at primary tumor." (PMID 37120615, 2023). "In contrast, TRPC5, TRPV1, and TRPV2 channels have been found to impede macrophage differentiation, suppress HCC cell proliferation, and ultimately decrease tumor cell invasiveness through the Akt/IκB/NF-κB signaling pathway, STAT3 pathway, and Akt/Nrf2 signaling pathway, respectively." (PMID 37569884, 2023).